EIF1AX (eukaryotic translation initiation factor 1A X-linked)
Description:
Component of the 43S pre-initiation complex (43S PIC), which binds to the mRNA cap-proximal region, scans mRNA 5'-untranslated region, and locates the initiation codon. This protein enhances formation of the cap-proximal complex. Together with EIF1, facilitates scanning, start codon recognition, promotion of the assembly of 48S complex at the initiation codon (43S PIC becomes 48S PIC after the start codon is reached), and dissociation of aberrant complexes. After start codon location, together with EIF5B orients the initiator methionine-tRNA in a conformation that allows 60S ribosomal subunit joining to form the 80S initiation complex. Is released after 80S initiation complex formation, just after GTP hydrolysis by EIF5B, and before release of EIF5B. Its globular part is located in the A site of the 40S ribosomal subunit. Its interaction with EIF5 during scanning contribute to the maintenance of EIF1 within the open 43S PIC. In contrast to yeast orthologs, does not bind EIF1.
Synonyms: eIF-4C; EIF1A; EIF4C; eIF-1A; EIF1AP1
Tractability: Small molecule: a structure with a bound ligand is known. PROTAC: ubiquitination databases record sites on it; its protein half-life has been measured.
Gene: Protein-coding gene on chromosome X (20,124,525 to 20,141,982, reverse strand). Ensembl gene ENSG00000173674.
Subcellular location: Cytoplasm
Subcellular location (Human Protein Atlas): Cytosol
Pathways (Reactome):
Metabolism of proteins: Formation of a pool of free 40S subunits; Formation of the ternary complex, and subsequently, the 43S complex; GTP hydrolysis and joining of the 60S ribosomal subunit; L13a-mediated translational silencing of Ceruloplasmin expression; Ribosomal scanning and start codon recognition; Translation initiation complex formation
Gene Ontology:
Molecular function: protein binding; RNA binding; translation factor activity, RNA binding; translation initiation factor activity
Biological process: ribosome assembly; translational initiation
Cellular component: eukaryotic 43S preinitiation complex; eukaryotic 48S preinitiation complex; multi-eIF complex; cytoplasm; cytosol
Homologues: Orthologues: dog EIF1AX (100% identical), guinea pig EIF1AX (100% identical), macaque EIF1AX (100% identical), mouse Eif1ax (100% identical), pig EIF1AX (99% identical), tropical clawed frog eif1ax (99% identical), zebrafish eif1axb (99% identical), rat Eif1ax (97% identical), zebrafish eif1axa (97% identical), Drosophila melanogaster eIF1A (79% identical), chimpanzee EIF1AX (76% identical), Caenorhabditis elegans eif-1.A (71% identical). Paralogues in human: EIF1AY (99% identical).
Diseases named in the same sentence as EIF1AX in open-access papers:
EIF1AX is named in the same sentence as 40 diseases in open-access papers, as found by Europe PMC text mining. Sharing a sentence is not in itself a finding about the gene and the disease. The quoted sentences say what the papers report.
uveal melanoma (26 papers, 2015 to 2025). A melanoma derived from melanocytes of the uveal tract. "Our analysis suggests that the majority of TWT cutaneous melanomas harbor a Ras/MAPK pathway mutation, with some confirmed cutaneous melanomas demonstrating mutations more commonly identified in uveal melanoma, including EIF1AX and GNAQ." (PMID 38611025, 2024). "On the other hand, mutations in eukaryotic translation initiation factor 1A X-Linked (EIF1AX) were found to be a protective factor in uveal melanoma metastasis." (PMID 35741122, 2022). "SF3B1 mutations are present in approximately 25% of malignant blue nevi and 15% of uveal melanomas while EIF1AX mutations are present in approximately 8% of malignant blue nevi and 24% of uveal melanomas." (PMID 35008286, 2021). "Cases of uveal melanoma with positive EIF1AX mutations rarely metastasize and other genetic alterations are thought to occur when metastasis does occur." (PMID 32429485, 2020). "BAP1-associated uveal melanomas are diagnosed in the age of 30–59 years and are associated with cutaneous melanomas and renal cell carcinomas, while EIF1AX gene variants are associated with thyroid and ovarian cancer." (PMID 32321466, 2020). "Autosomal dominant inheritance of pathogenic BAP1 gene variants have been observed in 47% of uveal melanomas, while pathogenic EIF1AX variants have been found in 14–20% of the cases." (PMID 32321466, 2020). "The reported frequency of EIF1AX gene mutation is in the range of 8–18.9% of primary uveal melanoma cases." (PMID 31109147, 2019). "EIF1AX has recently been reported as recurrently mutated in uveal melanomas, in mutual exclusion with mutations in SF3B1." (PMID 26506417, 2015). "Eukaryotic translation initiation factor 1A X-linked (EIF1AX) encodes a translation initiation factor, change-of-function or gain-of-function mutations (in exons 2, 5 and 6) of which were recognised originally in uveal melanomas." (PMID 34062862, 2021). "Finally, SF3B1 and EIF1AX mutations have been reported in primary leptomeningeal melanocytic neoplasms, thus suggesting a similarity between these tumors and uveal melanomas." (PMID 29156643, 2017). "The first mutation set encompasses the eight UM driver genes according to the TCGA study, divided into “uveal melanoma initiating mutations” (CYSLTR2, GNA11, GNAQ and PLCB4) and “second hit mutations with prognostic impact” (BAP1, EIF1AX, SF3B1 and SRSF2)." (PMID 39858540, 2025). "Recent basic and clinical research has figured out, that Uveal melanoma was characterized by a series of genetic mutations like the Gq pathway alterations, the gene BAP1, splice, and EIF1AX mutations (also known as the BSE event)." (PMID 36920166, 2023). "Loss of function mutations in BAP1, gain of function mutations in related EIF1AX and SF3B1, and chromosomal 8q gains have been identified as secondary driver mutations in uveal melanomas and are present in a subset of malignant blue nevi." (PMID 35008286, 2021). "Uveal melanoma has been thought to result from an initiating GNAQ/GNA11 mutation, followed by a secondary BSE event from mutations in the genes BAP1, SF3B1, and EIF1AX." (PMID 32429485, 2020). "In uveal melanoma, GNAQ and GNA11 gene mutations are frequently found and prognosis is based on mutation status of BAP1, SF3B1 and EIF1AX genes." (PMID 33396957, 2020). "Uveal melanomas, in contrast to conjunctival melanomas, lack BRAF or NRAS mutations but frequently have mutations in GNAQ, GNA11, BAP1, SF3B1 or EIF1AX." (PMID 28938534, 2017). "In our cohort of primary uveal melanomas from vfDNA+/UM+ patients, BAP1 alterations occurred throughout the entire gene, most of the SF3B1 mutations affected position p.R625, and EIF1AX mutations were found at various positions within the first two exons of the gene." (PMID 40240901, 2025).
uveal melanoma (continued). "Uveal melanoma (UM) has well-characterised somatic copy number alterations (SCNA) in chromosomes 1, 3, 6 and 8, in addition to mutations in GNAQ, GNA11, CYSLTR2, PLCB4, BAP1, SF3B1 and EIF1AX, most being linked to metastatic-risk." (PMID 32340176, 2020). "According to these findings, it was proposed that SF3B1 mutations help to define a subgroup of uveal melanomas associated with metastatic risk that is intermediate between uveal melanomas with BAP1 mutations (high risk) and uveal melanomas with EIF1AX mutations (low risk)." (PMID 29156643, 2017). "The progression of uveal melanoma relies on a second genetic driver event, such as the inactivation of BAP1 (about 60% of cases) on chromosome 3p21, mutation in the Splicing Factor 3b Subunit 1 (Spliceosome Factor SF3B1) (about 25% of cases), or EIF1AX mutation (about 15–17% of cases)." (PMID 38732371, 2024). "Both cases lacked mutations in the common uveal melanoma tumor suppressors, SF3B1, BAP1, and EIF1AX." (PMID 39804140, 2025). "Sequencing of SF3B1 and EIF1AX in ten uveal melanomas with disomy 3 who developed metastases showed that none of them displayed EIF1AX mutations, while 30% harbored a mutation in SF3B1." (PMID 29156643, 2017).
thyroid cancer (23 papers, 2015 to 2025). "EIF1AX mutations frequently co-occur with RAS mutations in advanced thyroid cancers, collectively driving tumorigenesis." (PMID 40363930, 2025). "EIF1AX mutations are detected in approximately 14% of thyroid cancers, with reported frequencies of 11% in poorly differentiated thyroid cancer (PDTC) and 9% in anaplastic thyroid cancer (ATC)." (PMID 40363930, 2025). "EIF1AX mutations are present in 11% of poorly differentiated thyroid cancers and anaplastic thyroid cancers and are almost invariably associated with oncogenic RAS mutations." (PMID 36589683, 2022). "One of such genes relevant to thyroid cancer is EIF1AX, which harbors mutations frequently affecting the splice sites between intron 5 and exon 6 of the gene." (PMID 32948110, 2021). "EIF1AX-A113splice variants, which are recurrent in advanced thyroid cancer, stabilize the PIC and enable a general increase in protein synthesis through ATF4-induced dephosphorylation of EIF2α." (PMID 31330784, 2019). "EIF1AX mutations also occur in papillary and anaplastic thyroid carcinoma and serous ovarian tumors." (PMID 28229253, 2017). "EIF1AX mutations have been detected at low frequency in a variety of cancer types reported in the TCGA studies (1.6% endometrial carcinoma, 1.5% thyroid carcinoma, 1.4% low grade glioma, 1.3% lung adenocarcinoma, 1.1% cutaneous melanoma (cBioPortal)." (PMID 26506417, 2015). "Interestingly, EIF1AX mutations in malignant Bethesda IV thyroid nodules appeared to be associated with more indolent forms of thyroid cancer." (PMID 39766147, 2024). "In addition to the 7 gene panel, Thyroseq suggest the search of several variants such as ALK, NTRK3 gene fusions and mutations of hTERT, EIF1AX that considered together account for 12% of all thyroid cancers." (PMID 32236306, 2020). "Interestingly, EIF1AX was found to harbor heterozygous mutations in papillary carcinomas, the most common thyroid cancer, and in ovarian carcinoma with a worse prognosis when coupled with mutations of the Ras family." (PMID 31330784, 2019). "EIF1AX mutations are missense mutations mainly clustered in the amino-terminal portion of the encoded protein with some frameshift deletions in UM and a splice site mutation hotspot in thyroid cancer." (PMID 28229253, 2017). "Of note, EIF1AX mutations were found almost exclusively in HRAS-, KRAS-, and NRAS-mutant thyroid cancers (p<0.05), whereas STK11 mutations were found in greater proportion of HRAS-mutant NSCLC compared to the other HRAS-mutant cancer types." (PMID 37503077, 2023). "EIF1AX was identified as a cancer driver gene in thyroid cancer." (PMID 36589683, 2022). "Molecularly, EIF1AX is essential for the assembly of 43S pre-initiation ribonucleoprotein complexes for protein synthesis; a mutant form of EIF1AX was able to increase general protein synthesis in thyroid carcinoma, which is consistent with higher protein synthesis demand in cancer cells." (PMID 34436011, 2021). "In another study, the integrative analysis of aggressive thyroid carcinomas, including ATC and advanced DTC, revealed the frequent presence of TERT, AKT1, PIK3CA, and EIF1AX mutations in combination with BRAFV600E and RAS mutations in these advanced forms of thyroid cancers." (PMID 32751138, 2020). "EIF1AX gene was recently identified as a new thyroid cancer-related gene." (PMID 31077238, 2019).
thyroid cancer (continued). "Furthermore, it was reported that of the nine malignant Bethesda IV nodules with EIF1AX mutations, five (55.6%) did not lead to aggressive thyroid cancer." (PMID 39766147, 2024). "The current research about the incidence, metastasis, and prognosis of thyroid cancer indicated that PIK3CA, PTEN, CDKN1B, TSHR, and EIF1AX were also involved, which should be considered in the multi-gene panel." (PMID 39600648, 2024). "Review articles discussing these models have been published, including examples of Hras or Kras knock-in mice crossed with cooperating genetic alterations commonly found in advanced thyroid cancers driven by oncogene RAS (e.g., NF2, EIF1AX and PI3K pathway genes)." (PMID 39874138, 2025).
melanoma (9 papers, 2016 to 2025). A malignant, usually aggressive tumor composed of atypical, neoplastic melanocytes. "MLPA was conducted to detect chromosomal alterations and Sanger sequencing used to identify point mutations in candidate melanoma driver genes (BRAF, NRAS, KRAS, GNA11, GNAQ), and other genes implicated in melanoma prognosis (EIF1AX, SF3B1)." (PMID 30558566, 2018). "Several recent studies have reported mutations in EIF1AX in different cancer types, including melanoma and thyroid and ovarian cancer." (PMID 26769193, 2016). "In this study, we examined POM for alterations in candidate melanoma driver genes (BRAF, NRAS, KRAS, GNA11, GNAQ) and genes implicated in UM prognosis (EIF1AX, SF3B1, BAP1)." (PMID 30558566, 2018). "In addition (and like SF3B1 mutations), the EIF1AX mutations in our cases occurred both in melanocytomas as well as melanomas, suggesting that they are not necessarily associated with worrisome histology, but the prognostic implications of these mutations remain to be elucidated." (PMID 26769193, 2016). "Eight other cases carried one or more mutations in genes also found in uveal or mucosal melanoma, but not in cutaneous melanoma: BAP1, SF3B1, or EIF1AX and hence were similarly suspect as misclassified." (PMID 34939927, 2021).
anaplastic thyroid cancers (7 papers, 2020 to 2025). "EIF1AX mutations have been documented in papillary, poorly differentiated, and anaplastic thyroid carcinomas as well as in benign thyroid nodules." (PMID 32976686, 2020). "The EIF1AX gene mutations have been recently associated with papillary thyroid carcinoma and anaplastic thyroid cancer." (PMID 32236306, 2020). "Furthermore, EIF1AX mutations, found in 5.4% of our samples, are associated with aggressive thyroid neoplasms, particularly anaplastic thyroid carcinoma, and their detection could inform risk stratification and treatment intensity for individual patients." (PMID 41590496, 2025). "Given the association of EIF1AX as a driver gene in papillary thyroid carcinoma (PTC) and the presence is some cases of anaplastic thyroid cancer (ATC), the patient was recommended to undergo thyroid surgery." (PMID 32236306, 2020).
cutaneous melanoma (6 papers, 2015 to 2025). A primary melanoma arising from atypical melanocytes in the skin. "UM tumors are frequently detected with mutations in GNA11, GNAQ, EIF1AX, BAP1, and SF3B1 instead of the typical mutations associated with cutaneous melanoma." (PMID 40283643, 2025).
thyroid tumor (6 papers, 2016 to 2025). A benign or malignant neoplasm affecting the thyroid gland. "The Cancer Genome Atlas (TCGA) study was the first landmark study to describe the mutation of EIF1AX (eukaryotic translation initiation factor 1A, X-linked) in thyroid tumors, more specifically in papillary thyroid carcinoma (PTC)." (PMID 36371345, 2022). "In order to have an overall understanding of EIF1AX mutation detected in thyroid tumors, we also analyzed the occurrence of EIF1AX mutations in the COSMIC database, cBioPortal for cancer genomics database and previous studies." (PMID 31077238, 2019). "As EIF1AX mutations have been recently found in various tumors, including thyroid tumors other than PTC, the identification of additional elements (e.g. miR-451a) linked to this gene is of general interest." (PMID 26871295, 2016). "Given the high allelic frequency of EIF1AX mutations in comparison to that of co-existing mutations, it has been suggested that EIF1AX mutations represent an early event, at least in some cases, that promotes initiation of the thyroid tumors and malignant transformation." (PMID 36371345, 2022). "As a result, we were not able to report the frequency of EIF1AX mutations in specific types of thyroid neoplasms including conventional PTC or ATC that usually correlate with Bethesda V or VI categories." (PMID 36371345, 2022).
ovarian carcinoma (5 papers, 2015 to 2025). A malignant neoplasm originating from the surface ovarian epithelium. "EIF1AX mutations have been reported in uveal melanomas, thyroid tumors, and ovarian carcinomas and are frequently located in the NTT domain." (PMID 36589683, 2022). "In agreement with the results in breast and ovarian cancer, to our knowledge, we demonstrated for the first time higher ectopic expression levels of EIF1AX protein in EC than in normal tissues and precancerous lesions." (PMID 36589683, 2022).
thyroid nodule (5 papers, 2019 to 2025). A small circumscribed mass in the THYROID GLAND that can be of neoplastic growth or non-neoplastic abnormality. "The aim of this study was to determine the prevalence, the risk of malignancy and the histopathological outcome of EIF1AX mutations in a series of FNA specimens from indeterminate thyroid nodules (Bethesda III and IV) with surgical follow-up." (PMID 36371345, 2022). "A 5-year retrospective analysis was performed on surgically resected thyroid nodules with identified EIF1AX mutations on molecular testing with ThyroseqV3®." (PMID 36371345, 2022). "Overall, data on the prevalence and phenotypic correlations of EIF1AX mutations in thyroid nodules is still limited." (PMID 36371345, 2022). "We investigated the prevalence of EIF1AX mutations and co-mutations in cytologically indeterminate thyroid nodules at our institution." (PMID 36371345, 2022). "In addition, TSHR, TTN, PIK3CA, and EIF1AX mutations in thyroid nodules categorized as indeterminate are uncommon and are typically verified as benign." (PMID 40586006, 2025). "However, data and clinical significance of EIF1AX mutations in thyroid nodules is still limited." (PMID 36371345, 2022). "Of note, Bethesda category V and VI thyroid nodules have a strong correlation with BRAF V600E mutations, whereas intermediate thyroid nodules categorized as Bethesda III and IV are associated with H, K, or NRAS or EIF1AX mutations, CNAs, or GEP." (PMID 39766147, 2024). "Thyroid nodules with CNAs alone or in conjunction with lower risk mutations such as HRAS, NRAS, DICER1, EIF1AX, and GEA are more likely to be low-risk neoplasms." (PMID 36551633, 2022).